VDAC1P4 (voltage dependent anion channel 1 pseudogene 4)
Synonyms: formerly VDAC4; VDAC4P
Gene: Processed pseudogene on chromosome 1 (180,434,800 to 180,435,936, forward strand). Ensembl gene ENSG00000235060.
Diseases named in the same sentence as VDAC1P4 in open-access papers:
VDAC1P4 is named in the same sentence as 2 diseases in open-access papers, as found by Europe PMC text mining. Sharing a sentence is not in itself a finding about the gene and the disease.
VDAC1P4 shares sentences with these, for which no sentence is quoted: Cognitive impairment (1 paper); tumor (1).